B3GALT4 (beta-1,3-galactosyltransferase 4)
Description:
Involved in GM1/GD1B/GA1 ganglioside biosynthesis.
Synonyms: Beta3Gal-T4; Beta3GalT4; GalT4; GALT2
Tractability: Antibody: UniProt predicts a signal peptide or a membrane-spanning region.
Gene: Protein-coding gene on chromosome 6 (33,277,123 to 33,284,832, forward strand). Ensembl gene ENSG00000235863.
Subcellular location: Golgi apparatus membrane
Pathways (Reactome):
Metabolism: Glycosphingolipid biosynthesis; Lewis blood group biosynthesis
Gene Ontology:
Molecular function: ganglioside galactosyltransferase activity; N-acetyl-beta-D-glucosaminide beta-(1,3)-galactosyltransferase activity; hexosyltransferase activity
Biological process: ganglioside biosynthetic process; glycosphingolipid biosynthetic process; oligosaccharide biosynthetic process; carbohydrate derivative metabolic process; glycoprotein biosynthetic process
Cellular component: Golgi membrane; membrane
Genetic constraint (gnomAD): Loss-of-function variants: 4 observed, 5.94 expected, observed/expected ratio (o/e) 0.67, 90% interval 0.33 to 1.5. That is too few expected variants to judge how well the gene tolerates losing a copy. Missense variants: 441 observed, 506.86 expected, observed/expected ratio (o/e) 0.87, 90% interval 0.8 to 0.94. Synonymous variants: 259 observed, 236.27 expected, observed/expected ratio (o/e) 1.1, 90% interval 0.99 to 1.22.
Homologues: Orthologues: macaque B3GALT4 (98% identical), rabbit B3GALT4 (86% identical), pig B3GALT4 (84% identical), dog B3GALT4 (83% identical), rat B3galt4 (79% identical), mouse B3galt4 (78% identical), guinea pig B3GALT4 (77% identical), tropical clawed frog b3galt4 (35% identical), zebrafish b3galt4 (31% identical), Drosophila melanogaster CG8668 (24% identical), Drosophila melanogaster CG8673 (22% identical), Caenorhabditis elegans B0024.15 (18% identical), and 12 more. Paralogues in human: B3GALT9 (28% identical), B3GNT4 (26% identical), B3GNT6 (25% identical), B3GNT9 (25% identical), B3GNT5 (24% identical), B3GALT5 (24% identical), B3GNT3 (24% identical), B3GALT1 (23% identical), B3GNT7 (23% identical), B3GNT8 (23% identical), B3GALT2 (23% identical), B3GALT6 (22% identical), and 3 more.
Diseases named in the same sentence as B3GALT4 in open-access papers:
B3GALT4 is named in the same sentence as 24 diseases in open-access papers, as found by Europe PMC text mining. Sharing a sentence is not in itself a finding about the gene and the disease. The quoted sentences say what the papers report.
colorectal cancer (4 papers, 2021 to 2025). A primary or metastatic malignant neoplasm that affects the colon or rectum. "Studies have demonstrated that B3GALT4 is associated with the prognosis of both ovarian cancer and colorectal cancer." (PMID 36284313, 2022). "In this study, we conducted an analysis and screening of potential core pathways, specifically the Glycosphingolipid pathway, and identified four core genes (SMPD1, GLTP, B3GALT4, and ST8SIA6) in colorectal cancer based on data analysis from relevant databases." (PMID 39898245, 2025).
neuroblastoma (4 papers, 2022 to 2025). Neuroblastoma (NB) is the most common solid, extracranial childhood tumor. "Our findings suggested that B3GALT4 could inhibit the progression of neuroblastoma, verifying the protective role of B3GALT4 in the risk signature." (PMID 36605200, 2022). "In neuroblastomas, based on overexpression of B3GALT4, forming GD1b from GD2, one report described enhanced recruitment of CD8+ T cells." (PMID 37670947, 2023). "Considering B3GALT4 serves as the connecting link of ganglioside in neuroblastoma, we further performed immunohistochemistry to validate the expression of B3GALT4 in clinical neuroblastoma specimens." (PMID 36605200, 2022). "Consistently, colony formation assay showed that neuroblastoma cells with downregulation of B3GALT4 present more cell clones than the control group in both cell lines." (PMID 36605200, 2022). "The role of the signature gene B3GALT4 in neuroblastoma was explored in vitro." (PMID 36605200, 2022). "Our results also showed the inhibition of B3GALT4 could significantly increase neuroblastoma cell proliferation, migration, and invasion in vitro." (PMID 36605200, 2022). "Considering B3GALT4 as the connecting link of ganglioside and with the highest absolute value of regression coefficient in signature genes, the siRNA of B3GALT4 was transfected into 9464D and 975A2 cells, and the role of B3GALT4 in neuroblastoma was explored." (PMID 36605200, 2022). "Additionally, neuroblastoma cells with downregulation of B3GALT4 present with increased proliferation, invasion, and metastasis abilities in vitro." (PMID 36605200, 2022). "However, the role of B3GALT4 in modulating the tumor microenvironment (TME) of neuroblastoma (NB) remains unknown." (PMID 36284313, 2022). "B3GALT4 is involved in synthesizing GM1/GD1 gangliosides and has been identified as a prognostic marker for osteosarcoma and neuroblastoma." (PMID 36605200, 2022).
breast carcinoma (3 papers, 2022 to 2025). "Moreover, our prior research demonstrated that B3GALT4 displayed elevated expression in breast cancer and was associated with tumor development." (PMID 40718832, 2025). "In this study, we validated the presence of GM1 on sEV derived from breast cancer cells, and explored the mechanism underlying the increased sEV secretion in B3GALT4-overexpressed cells and the vesicular GM1 induced EMT process in recipient cells by proteomic analysis." (PMID 35558506, 2022). "Therefore, B3GALT4 is strongly linked with the progression of breast cancer." (PMID 40718832, 2025). "In breast cancer cells, inhibition of the Smad3/4 complex binding to the B3GALT4 promoter SBE can lead to the down-regulation of the B3GALT4 gene expression, which in turn hinders the epithelial-mesenchymal transition process in breast cancer cells." (PMID 40718832, 2025). "The current study aimed to incorporate the ultrasonic features of primary tumors and the expression of B3GALT4 in tumor tissues to develop a model to predict ALNM in patients with breast cancer." (PMID 40718832, 2025). "In the present study, immunohistochemical analysis showed that the expression of B3GALT4 was higher in breast cancer tissues than in paired normal tissues." (PMID 35558506, 2022). "Additionally, our previous study has shown that B3GALT4 was markedly overexpressed in breast cancer tissues and had a strong correlation with certain characteristics of clinicopathological status and unfavorable prognosis." (PMID 40718832, 2025). "B3GALT4 could inhibit the epithelial-mesenchymal transition in breast cancer cells." (PMID 40718832, 2025). "Overexpression of B3GALT4 resulted in elevated vesicular GM1 levels and increased sEV secretion in breast cancer cells." (PMID 35558506, 2022).
melanoma (2 papers, 2015 to 2019). A malignant, usually aggressive tumor composed of atypical, neoplastic melanocytes. "In contrast, GM1/GD1b synthase (B3GALT4) showed very low expression in melanoma lines." (PMID 31611597, 2019). "Although the associations between B3GALT4 and ovarian and uterine corpus cancer, as well as melanoma have been reported 39,40, the function of this gene is not fully understood in cancers." (PMID 25924914, 2015).
type 1 diabetes (2 papers, 2014 to 2018). "The changed expression of B3GALT5, B3GALT4 and B4GALT1 suggest that the development of type 1 diabetes is associated with changes in the composition of islet glycosphingolipids with increases in the neolacto/lacto series and decreased levels of gangliosides." (PMID 29671030, 2018). "Although B3GALT4 mitigates ganglioside activity in neurodegenerative disorders, such as Huntington disease, it was also reported that gangliosides are related to the immunological pathophysiology of type 1 diabetes and to insulin resistance in type 2 diabetes." (PMID 25493549, 2014).
colon cancer (1 paper, 2021). "Over‐expression of B7‐H3 in colon cancer upregulates the B3GALT4 expression level." (PMID 34258887, 2021). "Therefore, B3GALT4 is a potential prognostic and treatment target for colon cancer." (PMID 34258887, 2021).
gynecological cancers (1 paper, 2021). "had confirmed that B3GALT4 was a promising biomarker for the diagnosis of gynecological cancers." (PMID 35071226, 2021).
cancer (4 papers, 2014 to 2025). A tumor composed of atypical neoplastic, often pleomorphic cells that invade other tissues. "Recently, an alternative approach was followed in which the glycosyltransferases ST3GAL2, ST3GAL3, B4GALT5, and B3GALT4 were suggested as a further predictor in identifying GD2-positive phenotypes in cancer patients." (PMID 36551537, 2022).
tumor (3 papers, 2022 to 2025). "The lipid raft inhibitor, MβCD, attenuated B3GALT4 deficiency-induced tumor progression and immune evasion." (PMID 36284313, 2022). "B3GALT4 expression level of the primary tumor was analyzed using quantitative real-time polymerase chain reaction (qRT-PCR)." (PMID 40718832, 2025). "The silencing and upregulation of B3GALT4 led to increased and decreased tumour proliferation and migration in vitro of 9464D cells, respectively." (PMID 37887559, 2023). "The upregulation of B3GALT4 in vivo (nude mouse xenografted with B3GALT4-expressing 9464D cells) led to tumour regression and the recruitment of CD8+ T cells." (PMID 37887559, 2023). "Rescue experiments demonstrated that blocking lipid rafts with MβCD reversed the inhibitory effect of B3GALT4 knockdown on tumor progression and the tumor microenvironment, indicating that B3GALT4 exerted its function through lipid rafts in NB." (PMID 36284313, 2022). "In accordance with the chemotaxis assay data, MβCD treatment enhanced the number of CD8+ T cells in tumor tissues of C57BL/6 mice treated with B3GALT4-knockdown 9464D cells." (PMID 36284313, 2022). "Together, our study uncovered the critical mechanism of B3GALT4-mediated tumor immunity, which is attraction of CD8+ T cells, and our results indicate that blockage of lipid rafts is a potential therapeutic target for NB." (PMID 36284313, 2022). "Subcutaneous tumor models with B3GALT4-knockdown 9464D cells confirmed that MβCD relieved the knockdown of B3GALT4-mediated tumor growth." (PMID 36284313, 2022). "In conclusion, the present study characterized a tumor-intrinsic function of B3GALT4 in remodeling the TME of NB." (PMID 36284313, 2022). "CCK-8, colony formation, and transwell assays and experiments in tumor-bearing mouse models were conducted to investigate the function of B3GALT4." (PMID 36284313, 2022). "Taken together, these data demonstrated that MβCD attenuated the knockdown of B3GALT4-induced tumor progression and immunosuppression." (PMID 36284313, 2022). "B3GALT4 is significantly overexpressed in many tumor tissues." (PMID 40718832, 2025). "Silencing B3GALT4 significantly enhanced tumor progression both in vitro and in vivo." (PMID 36284313, 2022). "Accordingly, these data provide strong evidence that B3GALT4 overexpression may promote CD8+ T lymphocyte recruitment into tumor sites via CXCL9 and CXCL10 in NB." (PMID 36284313, 2022). "Beta-1,3-galactosyltransferase-4 (B3GALT4) plays a critical regulatory role in tumor biology." (PMID 36284313, 2022). "Considering the heterogeneity of the tumor microenvironment, whether B3GALT4 also modulates the recruitment of other immune cells remains unknown." (PMID 36284313, 2022).
neurodegenerative disease (1 paper, 2022). A disorder of the central nervous system characterized by gradual and progressive loss of neural tissue and neurologic function. "Therefore, our results suggest a downregulation of the glycan structures, derived from B3GALT4, ST3GAL2 and/or SLC35A1 genes, with ageing, a feature so far only described in neurodegenerative diseases." (PMID 36009354, 2022).
B3GALT4 also shares sentences with these, for which no sentence is quoted: osteosarcoma (3 papers); ovarian carcinoma (2); dementia (1); diabetes (1); dyslipidemia (1); Huntington disease (1); hyperlipidemia (1); Hypertension (1); lung carcinoma (1); lymph node metastasis (1); metabolic disease (1); Parkinsonism (1); type 2 diabetes (1); uterine corpus cancer (1).